ENSG00000257355 (novel protein)
Gene: Protein-coding gene on chromosome 19 (12,017,888 to 12,052,967, reverse strand). Ensembl gene ENSG00000257355.
Genetic constraint (gnomAD): Missense variants: 72 observed, 80.6 expected, observed/expected ratio (o/e) 0.89, 90% interval 0.74 to 1.09. Synonymous variants: 29 observed, 29.2 expected, observed/expected ratio (o/e) 0.99, 90% interval 0.74 to 1.35.